SLC7A11 (solute carrier family 7 member 11)
Diseases named in the same sentence as SLC7A11 in open-access papers (continued):
Sharing a sentence is not in itself a finding about the gene and the disease.
ovarian carcinoma (85 papers, 2017 to 2026). A malignant neoplasm originating from the surface ovarian epithelium. "In recent years, SLC7A11 was found to be highly expressed in various solid tumours, including ovarian cancer and GBM, and is closely associated with treatment resistance." (PMID 40000422, 2025). "The potential diagnostic and therapeutic roles of GPAT4 and SLC7A11 in ovarian cancer are explored further in subsequent sections." (PMID 40722736, 2025). "This non-invasive approach holds promise for monitoring epigenetic alterations linked to SLC7A11 in ovarian cancer patients." (PMID 41438431, 2025). "While elevated SLC7A11 expression is associated with a poor prognosis in ovarian cancer patients, its diagnostic performance remains suboptimal." (PMID 40722736, 2025). "Elevated levels of SLC7A11 expression have been linked to unfavorable outcomes in multiple cancers, such as ovarian cancer." (PMID 40535572, 2025). "In fact, both these studies showed that low expression of SLC7A11 was associated with a poor overall survival in ovarian cancer patients." (PMID 38203758, 2024). "In patients with epithelial ovarian cancers, high co-expression of SLC7A11 and GPX4 has been substantially associated with poor overall survival and progression-free survival of affected patients." (PMID 38778030, 2024). "By boosting miR-382-5p to lower SLC7A11 and so preventing the proliferation, invasion, and transfer of ovarian cancer cells, lidocaine also causes a buildup of iron content and reactive oxygen species (ROS) in the OC." (PMID 39192972, 2024). "The promoter area of SLC7A11 is bound by SNAI2, and when SNAI2 is blocked, SLC7A11 expression is down-regulated, which causes ferroptosis in ovarian carcinoma cells." (PMID 39192972, 2024). "SLC7A11 was first linked to cisplatin resistance in ovarian cancer and has since been studied in multiple other cancer types." (PMID 38023731, 2023). "SLC7A11 serves as an independent indicator of poor prognosis in acute myeloid leukemia and an independent risk factor in ovarian cancer." (PMID 35280777, 2022). "Conversely, a recent study showed that low expression of SLC7A11 was associated with resistance to paclitaxel and a low survival rate in ovarian cancer patients." (PMID 36552652, 2022). "Background/Objectives: This study aimed to determine whether the expression levels of GPAT4 and SLC7A11 are associated with survival outcomes and platinum resistance in epithelial ovarian cancer (EOC) patients." (PMID 40722736, 2025). "Another recent research demonstrated that inhibition of NMD induced by stress could lead to upregulation of the cystine/glutamate exchanger SLC7A11, which has been associated with platinum resistance in ovarian cancer." (PMID 37223641, 2022). "Thus, ARID1A-deficient ovarian cancers may be susceptible to drugs targeting GCLC since their efficiency is enhanced by a low SLC7A11 expression that keeps GSH content at low levels." (PMID 38203758, 2024). "Overall, our results indicate that KIF26B is crucial for ovarian cancer progression and chemotherapy resistance, likely through SLC7A11 regulation." (PMID 41751488, 2026). "The study revealed that GPAT4/SLC7A11 is related to drug resistance and a poor prognosis in ovarian cancer." (PMID 40722736, 2025). "For example, circSnx12 contributes to cisplatin resistance by inhibiting ferroptosis through sponging the miR-194-5p/SLC7A11 axis in ovarian cancer." (PMID 40630134, 2025). "CYLD did not influence the expression levels of RIP3 (necrosis marker), p62 and ATG5 (autophagy marker), as well as levels of GPX4 and SLC7A11 (ferroptosis marker) in ovarian cancer A2780 and OVCAR3 cell lines." (PMID 40012003, 2025).
ovarian carcinoma (continued). "For example, in ovarian cancer, targeting SLC7A11 has been demonstrated to induce ferroptosis, offering a potential strategy for treating patients who are resistant to standard chemotherapy." (PMID 40535572, 2025). "Recent studies have identified SLC7A11, a key component of amino acid metabolism, as a potential biomarker for platinum resistance in ovarian cancer." (PMID 40722736, 2025). "Our research has revealed that the mode of cell death in ovarian cancer cells under glucose starvation is closely related to SLC7A11 expression." (PMID 41438431, 2025). "We next assessed the prognostic value of SLC7A11 expression in clinical lung and ovarian cancer cohorts, each comprising substantial numbers of cases with both low and high expression levels." (PMID 40784667, 2025). "The high expression of GPAT4 or SLC7A11 has been demonstrated to correlate with a poor prognosis in ovarian cancer patients from the TCGA-OC cohorts." (PMID 40722736, 2025). "The in vitro results revealed that GPAT-IN-125 (a glycerol-3-phosphate acyltransferase isoform inhibitor) and erastin (an SLC7A11 inhibitor) significantly decreased the viability of ovarian cancer cells and inhibited their proliferation." (PMID 40722736, 2025). "In this study, GPAT4 was significantly superior to SLC7A11 as a stand-alone predictor of platinum-resistant ovarian cancer drug resistance (SLC7A11 IHC score AUC 0.908, SLC7A11 expression grouping AUC 0.874)." (PMID 40722736, 2025). "Immunohistochemical analysis of SLC7A11 in ovarian cancer tissue revealed a median IHC score of 6 for SLC7A11 in platinum-resistant ovarian cancer and a median IHC score of 4 in platinum-sensitive ovarian cancer (p < 0.001)." (PMID 40722736, 2025). "In ovarian cancer, circSnx12 inhibits ferroptosis and renders ovarian cancer cells resistant to cisplatin treatment via the miR-194-5p/SLC7A11 axis." (PMID 40630134, 2025). "Our study provides inaugural evidence that USP43 orchestrates ferroptosis susceptibility in ovarian cancer, mechanistically delineating its governance of the FASN-HIF1α-SLC7A11 signaling axis." (PMID 40890129, 2025). "Previous work has shown that ferroptosis resistance mechanisms play a significant role in platinum resistance in ovarian cancer, and SLC7A11, a ferroptosis protective protein, can predict platinum resistance in ovarian cancer patients to some extent." (PMID 40722736, 2025). "The GPAT inhibitor (GPAT-IN-1) and an SLC7A11 inhibitor (erastin) attenuated platinum resistance in ovarian cancer cells, and their combined application increased cytotoxicity." (PMID 40722736, 2025). "In this review, we provide an overview of the current literature regarding the role of SLC7A11 in ovarian cancer to provide new insights on SLC7A11 modulation and evaluate the potential role of SLC7A11 as a therapeutic target." (PMID 38203758, 2024). "The expression of SLC7A11 is also upregulated in ovarian cancer tissues, playing a critical role in promoting resistance to ferroptosis by enhancing cystine uptake and supporting GSH biosynthesis." (PMID 39534872, 2024). "SLC7A11 expression is also increased in ovarian cancer tissues, suggesting a possible role of this protein as a therapeutic target." (PMID 38203758, 2024). "In this study, the authors found that the level of lncRNA As-SLC7A11 was significantly decreased in epithelial ovarian cancer (EOC) tissues compared to normal tissues." (PMID 38203758, 2024). "Another study found that patients with epithelial ovarian cancer (EOC) and a high co-expression level of SLC7A11 and GPX4 had a 60-fold higher risk of developing platinum resistance compared with patients with a low level of co-expression." (PMID 38203758, 2024).
ovarian carcinoma (continued). "In fact, two studies reported an increased expression of SLC7A11, while two different studies reported a decreased expression of SLC7A11 in chemotherapy-resistant ovarian cancer tissues and cell lines." (PMID 38203758, 2024). "Although SYVN1 mediates erastin-induced ferroptosis in ovarian cancer cells by facilitating ubiquitination-dependent degradation of SLC7A11, direct evidence for SYVN1-dependent NFE2L2 degradation during ferroptosis remains limited." (PMID 39534872, 2024). "CircRNASnx12 improves immunomodulatory resistance in ovarian cancer by targeting miR-194-5p/SLC7A11 pathways to block ferroptosis." (PMID 39192972, 2024). "Qin and colleagues reported that SLC7A11 protein expression was significantly increased in ovarian cancer tissues and cisplatin-resistant A2780/DDP and SKOV3/DDP cells compared to the cisplatin-sensitive cells." (PMID 38203758, 2024). "Overexpression of SLC7A11 has been reported in various cancers, including lung, breast, and ovarian cancers, where it contributes to tumor growth, chemoresistance, and poor prognosis." (PMID 39350768, 2024). "The aim of this review is to provide an overview of the current literature regarding the role of SLC7A11 in ovarian cancer in order to provide new insights into SLC7A11 modulation and to evaluate the potential role of SLC7A11 as a therapeutic target." (PMID 38203758, 2024). "In summary, we found that CEBPG promoted ovarian tumor cell proliferation and inhibited ferroptosis in vitro and accelerated tumor growth in vivo, and the promotion of ovarian cancer by CEBPG is partially dependent on SLC7A11." (PMID 37210575, 2023). "HRD1 was found to inhibit the proliferation and colony formation of ovarian cancer cells by inducing ferroptosis through facilitation of ubiquitination-dependent SLC7A11 degradation." (PMID 38072908, 2023). "In ovarian cancer, lidocaine down-regulated SLC7A11 expression by increasing miR-382-5p expression, to attenuate invasion and migration of ovarian cancer." (PMID 37829798, 2023). "Epithelial ovarian cancer patients with high co-expression of SLC7A11 and GPX4 are predicted to have unfavorable survival and platinum resistance." (PMID 37765018, 2023). "In contrast, SLC7A11 was significantly decreased in 90 drug-resistant ovarian cancer tissues compared with their controls, conferring drug resistance by inhibition of cell autophagy as a competing endogenous RNA." (PMID 35804831, 2022). "Inhibition of SLC7A11 induced ferroptosis significantly sensitized BRCA wild-type ovarian cancer cells to Olaparib." (PMID 36438923, 2022). "Low expression of SLC7A11 was found in 90 drug-resistant ovarian cancer cell tissues, resulting from that, SLC7A11 strongly regulated cell autophagy as a competing endogenous RNA." (PMID 36552652, 2022). "For in vitro experiments, SLC7A11 and GPX4 expression were both upregulated in platinum‐resistant cells compared with their parental ovarian cancer cells, and siRNA‐induced SLC7A11 and GPX4 inhibition decreased platinum resistance." (PMID 36485069, 2022). "Mechanistically, lidocaine upregulated miR-382-5p, which in turn suppressed SLC7A11 expression and triggered ferroptosis in ovarian cancer cells." (PMID 36438923, 2022). "Upregulation of SLC7A11 significantly increased the sensitivity of ovarian cancer cells to paclitaxel in vitro." (PMID 35804831, 2022). "Ferroptosis inducers increase the sensitivity of BRCA-proficient ovarian cancer cells to PARP inhibitor by repressing SLC7A11." (PMID 35805124, 2022). "The knockdown of AS-SLC7A11 increases the expression of SLC7A11 and improves the proliferation and viability of ovarian cancer cells." (PMID 33849550, 2021). "Another recent study showed that the antisense lncRNA As-SLC7A11 also regulates ovarian cancer cell migration by targeting Slc7a11 expression." (PMID 33433832, 2021). "Antisense lncRNA As-SLC7A11 suppresses epithelial ovarian cancer progression mainly by targeting SLC7A11." (PMID 33519933, 2021).
ovarian carcinoma (continued). "Our work suggested a miR-382-5p/SLC7A11 regulatory axis mediating lidocaine-induced ferroptosis in breast and ovarian cancer, provided new basis for therapy of female malignancies." (PMID 34122108, 2021). "The overexpression of SLC7A11 increased the paclitaxel sensitivity of paclitaxel-resistant ovarian cancer cells HeyA8-R, induced cell apoptosis, and arrested the cell cycle." (PMID 34790572, 2021). "A recent study demonstrates the regulation of cysteine/glutamate transporter by a lncRNA named As-SLC7A11, which is markedly reduced in epithelial ovarian cancer." (PMID 31191327, 2019). "SLC7A11, as an inhibitor of ferroptosis, may be a new therapeutic target for platinum-resistant ovarian cancer patients." (PMID 40722736, 2025). "In our study, we identify high SLC7A11 expression to significantly associate with poorer overall survival in lung but not ovarian cancer." (PMID 40784667, 2025). "Moreover, the combination of GPAT4 and SLC7A11 was found to be a novel marker predicting platinum resistance in ovarian cancer." (PMID 40722736, 2025). "In addition, the PARP inhibitor olaparib is used in combination with ferroptosis inducers to enhance the sensitivity of BRCAproficient ovarian cancer cells to olaparib by inhibiting solute carrier family 7 member 11 (SLC7A11)‐mediated GSH synthesis." (PMID 40866937, 2025). "Thus, targeting the USP43-FASN-HIF1α-SLC7A11 axis can inhibit ferroptosis and promote platinum sensitivity in ovarian cancer." (PMID 40890129, 2025). "However, as a sole predictor, SLC7A11 contributes minimally to platinum resistance in ovarian cancer." (PMID 40722736, 2025). "As an upregulated circRNA in chemoresistant ovarian cancer tissues compared to sensitive ones, circSnx12 knockdown enhances the chemosensitivity and increases apoptosis and ferroptosis of cisplatin chemoresistant ovarian cancer cells circSnx12/miR-194-5p/SLC7A11 axis." (PMID 38778030, 2024). "Additionally, the PARP inhibitor olaparib synergizes with FINs by inhibiting SLC7A11 in BRCA-proficient ovarian cancer." (PMID 38378601, 2024). "Moreover, SLC7A11 overexpression synergizes with ferroptosis inducers to enhance sensitivity to PARP inhibitors in BRCA-positive ovarian cancer patients." (PMID 38831301, 2024). "Furthermore, low SLC7A11 expression was correlated with poor overall survival, progression-free survival and post-progression survival in ovarian cancer patients." (PMID 38203758, 2024). "Therefore, the overexpression of SLC7A11 in ovarian cancer cells enhances GPX4 activity by increasing GSH levels, which assists cells in resisting ferroptosis and promotes cancer cell proliferation, invasion, and chemoresistance." (PMID 39045454, 2024). "Thus, HRD1 inhibited tumor formation and promoted ferroptosis in ovarian cancer cells by enhancing SLC7A11 degradation." (PMID 38203758, 2024). "Thus, specific clinical trials assessing the effects of SLC7A11 modulation (e.g., with natural or synthetic compounds) in ovarian cancer patients are needed to improve the outcomes of this disease." (PMID 38203758, 2024). "Thus, SNAI2 can inhibit ferroptosis by blocking SLC7A11 expression and can therefore promote ovarian cancer progression." (PMID 38203758, 2024). "Thus, lncRNA ADAMTS9-AS1 can attenuate ferroptosis by targeting the miR-587/SLC7A11 axis in ovarian cancer cell lines, thereby providing a new therapeutic target for the treatment of these patients." (PMID 38203758, 2024). "Thus, lidocaine can promote ferroptosis by modulating the miR-382-5p/SLC7A11 axis in ovarian cancer cells." (PMID 38203758, 2024).
ovarian carcinoma (continued). "In addition, recent studies indicate that ovarian cancer cells upregulate anti-ferroptosis factors such as Solute Carrier Family 7 Member 11 (SLC7A11, also known as xCT), providing insights into its modulation and potential as a therapeutic target." (PMID 39061859, 2024). "Meanwhile, Snail2 regulates ferroptosis through the regulation of SLC7A11 in ovarian cancer." (PMID 36699318, 2023). "Notably, a prognostic grading model for ovarian cancer has been established by certain scholars, incorporating five ferroptosis-associated factors (ALOX12, ACACA, SLC7A11, FTH1, CD44) through biological analysis." (PMID 38028615, 2023). "Among these 11 DGs, SLC7A11 can affect non-small cell lung cancer, renal cell carcinoma, prostate cancer progression through ferroptosis, and WASF2 is associated with poor ovarian cancer prognosis." (PMID 38035071, 2023). "The anesthetic lidocaine downregulates the expression of SLC7A11 in a dose-dependent manner by promoting the intracellular expression of microRNA-382-5p (miR-382-5p), and the inhibition of miR-382-5P blocked ferroptosis in ovarian cancer cells." (PMID 36090052, 2022). "In the study of Cai, inhibition of ADAMTS9-AS1 promoted the expression of miR-587, and overexpression of miR-587 enhanced the inhibition of SLC7A11 expression, ultimately promoted ferroptosis, and inhibited the proliferation and migration of ovarian cancer cells." (PMID 36438923, 2022). "So, SNAI2 knockdown may induce ferroptosis and inhibit the progression of ovarian cancer by downregulating SLC7A11." (PMID 36438923, 2022). "Moreover, recent studies have shown that ovarian cancers with wild‐type BRCA are sensitive to targeted‐SLC7A11 ferroptosis inducers." (PMID 36485069, 2022). "Furthermore, the treatment of lidocaine repressed tumor growth of ovarian cancer cells in vivo, in which the miR-382-5p expression was increased while SLC7A11 expression was decreased." (PMID 34122108, 2021). "Finally, external validation in larger, independent patient cohorts and prospective clinical studies will be essential to confirm the prognostic and predictive value of GPAT4/SLC7A11 co-expression, particularly in the context of platinum resistance in epithelial ovarian cancer (EOC)." (PMID 40722736, 2025). "In conclusion, SLC7A11 could be a potential therapeutic target in ovarian cancer since it plays a key role in improving cancer cells’ response to chemotherapeutic agents in both sensitive and resistant ovarian cancer cells." (PMID 38203758, 2024). "Thus, although SLC7A11 could be a potential therapeutic target in ovarian cancer treatment, more studies are required to evaluate the role of SLC7A11 expression as a biomarker in ovarian cancer management." (PMID 38203758, 2024). "In fact, an interesting study found that the inhibition of the Xc− transport system via the silencing of SLC7A11 expression (with siRNA) in SKOV3 ovarian cancer cells decreased sensitivity to L-alanosine, supporting the hypothesis that L-alanosine is an SLC7A11 substrate." (PMID 38203758, 2024). "Therefore, a link may exist between high expression levels of SLC7A11, ferroptosis and platinum resistance in ovarian cancer." (PMID 36485069, 2022). "Moreover, SNAI2 could directly bind to SLC7A11 promoter and regulate SLC7A11 expression, which might be the potential mechanism underlying SNAI2-regulated ferroptosis in ovarian cancer." (PMID 35220872, 2022).